IPP (intracisternal A particle-promoted polypeptide)
Description:
May play a role in organizing the actin cytoskeleton.
Synonyms: KLHL27
Tractability: Small molecule: it belongs to a druggable protein family. PROTAC: ubiquitination databases record sites on it.
Gene: Protein-coding gene on chromosome 1 (45,694,324 to 45,750,653, reverse strand). Ensembl gene ENSG00000197429.
Subcellular location: Cytoplasm, cytoskeleton
Gene Ontology:
Molecular function: actin binding; ubiquitin-like ligase-substrate adaptor activity
Biological process: proteasome-mediated ubiquitin-dependent protein catabolic process
Cellular component: actin cytoskeleton; Cul3-RING ubiquitin ligase complex; cytoplasm; cytoskeleton
Genetic constraint (gnomAD): Loss-of-function variants: 29 observed, 41.35 expected, observed/expected ratio (o/e) 0.7, 90% interval 0.52 to 0.96. The upper end of that interval is the gene's LOEUF score, 0.96, which puts it in group 4 of 6, group 1 being the genes least tolerant of losing a copy. Missense variants: 516 observed, 581.62 expected, observed/expected ratio (o/e) 0.89, 90% interval 0.82 to 0.95. Synonymous variants: 182 observed, 200.58 expected, observed/expected ratio (o/e) 0.91, 90% interval 0.8 to 1.03.
Homologues: Orthologues: dog IPP (97% identical), pig IPP (96% identical), chimpanzee IPP (95% identical), guinea pig IPP (95% identical), macaque IPP (94% identical), mouse Ipp (93% identical), rat Ipp (90% identical), rabbit IPP (85% identical), tropical clawed frog ipp (70% identical). Paralogues in human: KLHL20 (36% identical), KLHL12 (34% identical), KLHL2 (33% identical), KEAP1 (33% identical), KLHL17 (33% identical), KLHL3 (33% identical), KLHL4 (33% identical), KLHL5 (32% identical), KLHL1 (32% identical), KLHL28 (31% identical), KLHL18 (31% identical), KLHL8 (30% identical), and 42 more.
Diseases named in the same sentence as IPP in open-access papers:
IPP is named in the same sentence as 28 diseases in open-access papers, as found by Europe PMC text mining. Sharing a sentence is not in itself a finding about the gene and the disease. The quoted sentences say what the papers report.
breast carcinoma (4 papers, 2013 to 2020). "This study was designed to identify miRs targeting RSU1, or members of the IPP complex, and their activity in normal breast and luminal breast cancer cell lines." (PMID 32751711, 2020). "IPP production differed markedly between different human breast cancer cell lines post-ZA treatment." (PMID 30808421, 2019). "This may constitute a novel mechanism for the regulation of the PTEN/PI3K/AKT signaling pathway by miR-182-5p and -409-3p, via the targeting of RSU1 and the IPP cell adhesion complex in mammary epithelial and breast cancer cells." (PMID 32751711, 2020). "Compared to FRAX486, IPP-14 induced reduction of viability in two kinds of NF2-impaired cell lines, MDA-MB-231 (human breast cancer cells) and ACHN (human renal cancer cells)." (PMID 28423593, 2017). "Previous study showed that syntenin positively regulates the ILK adaptor function for the assembly of integrin β1/IPP signaling complexes, which activate integrin signaling pathways, including AKT, ERK1/2, and Rac1, in breast cancer cells." (PMID 23786877, 2013). "Estrogen receptor positive breast cancer cell lines, such as MCF-7, produced higher IPP levels than estrogen receptor negative cell lines, such as MDA-MB-231." (PMID 30808421, 2019).
diabetes (4 papers, 2012 to 2021). "ROS has been implicated in caspase-1 activation during various patho-physiological conditions like diabetes; ROS production was essential for inflammasome formation by glucose, IPP and fatty acids." (PMID 22295065, 2012). "In addition, the well-known anti-hypertensive tripeptide, IPP, was the only one able to inhibit the three digestive enzymes, highlighting its possible new and pivotal role in diabetes management." (PMID 34205680, 2021). "Since ILK or IPP is highly upregulated in multiple diseases, such as cancer, diabetes, and heart failure, our findings also open the door for developing unique therapeutic inhibitors of ILK, not as a kinase, but as a pseudokinase, by targeting at its Mg-ATP site or its binding to other proteins." (PMID 30367047, 2018).
Hypertension (3 papers, 2015 to 2020). The presence of chronic increased pressure in the systemic arterial system. "Two tripeptides, VPP and IPP from casein have been shown to significantly reduce high blood pressure in humans." (PMID 28445415, 2017).
atherosclerosis (2 papers, 2015 to 2024). A disease characterized by the build-up of fatty material and calcium deposition in the arterial wall resulting in partial or complete occlusion of the arterial lumen. "It was found that administration of VPP and IPP might be beneficial for preventing atherosclerosis due to the activity of ACE and hypercholesterolemia." (PMID 38672494, 2024). "In addition, IPP and VPP further inhibited inflammatory signaling by TNFα, a major pro-inflammatory cytokine involved in the pathology of atherosclerosis and other inflammatory diseases." (PMID 25714093, 2015).
Insulin resistance (2 papers, 2019 to 2024). Increased resistance towards insulin, that is, diminished effectiveness of insulin in reducing blood glucose levels. "Two well-known milk protein-derived peptides, IPP and VPP, demonstrated effective enhancement of insulin signals and anti-inflammation via the NF-κB pathway under TNF stimulation and prevention of insulin resistance." (PMID 38672494, 2024). "Of note, recent in vitro data using preadipocytes revealed that the tripeptides IPP (Ile-Pro-Pro) and VPP (Val-Pro-Pro), which are derived from milk casein, enhance insulin sensitivity and contribute toward the prevention of insulin resistance in the presence of tumor necrosis factor." (PMID 31340611, 2019).
malaria (2 papers, 2018 to 2022). Malaria is a serious and sometimes fatal disease caused by a parasite that commonly infects a certain type of mosquito which feeds on humans. "This may highlight the apicoplast FASII as a relevant drug target for malaria, despite the findings pointing to IPP synthesis as the only essential apicoplast function in nutrient-rich in vitro blood-stage studies." (PMID 35718642, 2022).
Obesity (2 papers, 2024). Accumulation of substantial excess body fat. "In the IPP networks, the presence of Akt3 and Mapk1 mediators as crossover points among pathogenic pathways was consistent, suggesting the crucial role of PI3K/AKT and MAPK signaling pathways commanding the complex pathogenesis of obesity." (PMID 39484291, 2024). "Bovine casein-derived tripeptides IPP and VPP from casein hydrolyzate have been reported to prevent obesity-induced chronic adipose inflammation in both animal models and cell cultures." (PMID 38672494, 2024).
Sepsis (2 papers, 2022 to 2025). Sepsis is defined as life-threatening organ dysfunction caused by a dysregulated host response to infection. "Next, we demonstrated that sepsis induces the upregulation of key components of the IRC/IPP complex in the hindlimb muscles of mice." (PMID 41385533, 2025). "Through multi-cohort analysis using ComBat co-normalization on microarray data in a heterogeneous group of sepsis patients, we found that the IPP gene set, when assayed at day 1 following hospital admission, can reliably predict all-cause 30-day mortality." (PMID 35847809, 2022). "Overall, these results demonstrate that the IPP gene set can capture similar information on 30-day mortality in sepsis as the total gene pool common to 17 microarrays, but with the potential to deliver actionable results in less than an hour, directly at the point of care." (PMID 35847809, 2022). "However, the performance of the whole IPP gene set to predict 30-day mortality in sepsis has not been evaluated in a large heterogeneous cohort of sepsis patients." (PMID 35847809, 2022).
breast tumor (1 paper, 2025). "The expression of IPP was significantly increased in the human breast tumor samples compared with the non-cancer tissues." (PMID 40438593, 2025).
cholangiocarcinoma (1 paper, 2024). A carcinoma that arises from the intrahepatic biliary tree (intrahepatic cholangiocarcinoma) or from the junction, or adjacent to the junction, of the right and left hepatic ducts (hilar cholangiocarcinoma). "According to the accumulation of IPP within zoledronate-treated cancer cells, expanded Vγ9Vδ2 T cells expressed higher cytotoxic functions against zoledronate-treated cholangiocarcinoma cell lines compared to non-treated cells." (PMID 38221530, 2024).
colitis (1 paper, 2022). Inflammation of the colon. "Furthermore, food protein-derived VPP and IPP inhibit colitis through NF-κB and MAPK pathways." (PMID 35911761, 2022).
COVID-19 (1 paper, 2022). A disease caused by infection with severe acute respiratory syndrome coronavirus 2. "The IPP gene set revealed significant changes in inflammation and cellular-associated transcriptomic markers in COVID-19 patients when compared with healthy volunteers." (PMID 36389738, 2022). "Non-supervised clustering using principal component analysis (PCA) on the 26 IPP mRNA transcripts resulted in clear distinct clusters between the 309 critically ill COVID-19 patients at admission and 49 healthy donors." (PMID 36389738, 2022). "Overall, these first results indicated that the IPP gene set provided relevant information recapitulating immune dysregulation known in COVID-19 critically ill patients, in line with the vast literature previously published on this population." (PMID 36389738, 2022).
gastric cancer (1 paper, 2017). A primary or metastatic malignant neoplasm involving the stomach. "To avoid the random cytotoxicity and false positive reaction of chemicals, we checked the cytotoxic effect of a group of chemicals including IPP-14 on PAK1 overexpressed pancreatic cancer cell line, MIA-Paca2, comparing to human gastric cancer cell line, MKN45." (PMID 28423593, 2017).
hearing loss (1 paper, 2019). "This study is the largest GWAS meta-analysis of ARHI to date and identified 7 associated loci, of which 5 are novel (FXYD5, IPP, SPIRE2, SPTBN1 and TRIL) and 2 have been previously related to hearing loss (ILDR1, ISG20)." (PMID 31645637, 2019).
heart failure (1 paper, 2016). Inability of the heart to pump blood at an adequate rate to meet tissue metabolic requirements. "We and others depicted that loss of each of the IPP-complex components leads to IPP-complex destabilization, reduced PKB phosphorylation and finally heart failure in zebrafish, mice and humans." (PMID 26954676, 2016). "Loss of one of the IPP-complex components results in destabilization of the whole complex, defective PKB signaling and finally heart failure." (PMID 26954676, 2016). "Interestingly, mutations within IPP-complex components lead to destabilization of the complex, reduced phosphorylation of PKB and finally heart failure, similar to Paxillin morphants." (PMID 26954676, 2016). "However, as shown here, Paxillin seems not to mediate its effect on cardiac function via IPP-signaling, since neither IPP-complex stability nor IPP-dependent PKB activation was altered in Paxillin-associated heart failure." (PMID 26954676, 2016). "Here, we show that targeted gene inactivation of Paxillin results in progressive decrease of cardiac contractility and heart failure in zebrafish without affecting IPP-complex stability and PKB phosphorylation." (PMID 26954676, 2016).
lung adenocarcinoma (1 paper, 2022). A carcinoma that arises from the lung and is characterized by the presence of malignant glandular epithelial cells. "In lung adenocarcinoma, as reported, ILK can regulate KRAS, IPP complex and Ras suppressor-1 (RSU1) to promote cancer cell multiplication, migration and epithelial-mesenchymal transition (EMT), and its high expression is pertinent to poor prognosis." (PMID 35029589, 2022).
pneumothorax (1 paper, 2023). Abnormal presence of air in the pleural cavity. "Pneumothorax was detected on IPP-CT and 1HR-CXR in 89.4% (76/85) and 100% (85/85), respectively." (PMID 37075048, 2023). "Similarly, in our study, most pneumothorax was detected on IPP-CT (89.4%), only slightly more than half of pneumothoraces persisted on 1HR-CXR, and only a small number of that group required chest tube placement." (PMID 37075048, 2023). "In the group without pneumothorax on IPP-CT or 1HR-CXR, no patient necessitated further imaging follow-up or returned to the hospital for symptoms related to delayed pneumothorax." (PMID 37075048, 2023). "Among all cases of pneumothorax detected on IPP-CT, 51.3% (39/76) completely resolved on 1HR-CXR without needle aspiration or chest tube placement." (PMID 37075048, 2023). "For those without pneumothorax on IPP-CT, a 1HR-CXR may only be necessary if the patient develops symptoms associated with potential pneumothorax." (PMID 37075048, 2023). "If no pneumothorax is identified on IPP-CT, follow-up 1HR-CXR may be required only for those who develop symptoms of pneumothorax." (PMID 37075048, 2023).
cancer (7 papers, 2018 to 2025). A tumor composed of atypical neoplastic, often pleomorphic cells that invade other tissues. "Apart from structural remodeling of the ECM scaffold, the cell mechanical cues on the ECM network are important players in the malignant progression of cancers, including elevated motility via the IPP complex created by focal adhesion adaptor proteins, such as PINCH1, ILK-1 and Parvin." (PMID 37287457, 2023).
tumor (6 papers, 2014 to 2023). "Deregulation of the isoprenoid pathway in some tumors leads to IPP over-production that is detected and considered as a tumor antigen by Vγ9Vδ2 TCR." (PMID 25538706, 2014). "As a consequence, Vγ9Vδ2 T cells can kill a variety of cancer cells because they sense the increased levels of IPP, but they do not depend on recognition of tumor-specific or tumor-associated antigens." (PMID 37980330, 2023). "For instance, an inhibitor targeting the interaction interface of ILK:Parvin complex could be highly appreciated because IPP complex formation seems to be essential for the well-being of tumor cells." (PMID 35089438, 2022). "On the other hand, such compound should be precisely delivered to tumor tissue as ILK and IPP are important for normal cells' proper functioning." (PMID 35089438, 2022). "Vδ2+ T cells are activated by cells that accumulate HMBPP and/or IPP and can also be stimulated through receptors NKG2D and DNAM-1 of various stress-induced molecules expressed on tumor cells including MICA/B, UL16-binding proteins (ULBP1–6), Nectin-2, and PVR, respectively." (PMID 36851283, 2023).
metabolic disease (2 papers, 2015 to 2024). A congenital disorder (due to inherited enzyme abnormality) or acquired (due to failure of a metabolically important organ) disorder resulting from an abnormal metabolic process. "Two milk protein-derived tripeptides, IPP and VPP, were meticulously studied concerning their effects on biomarkers of metabolic diseases." (PMID 38672494, 2024). "In this study, we examined the effects of IPP and VPP on 3T3-F442A murine pre-adipocytes, a widely used model for studying metabolic diseases." (PMID 25714093, 2015). "Taken together, our findings suggest that IPP and VPP exert insulin-mimetic adipogenic effects and prevent inflammatory changes in adipocytes, which may offer protection against metabolic disease." (PMID 25714093, 2015). "Therefore, it may be realized that both IPP and VPP can modulate blood glucose levels and may have an impact on glucose-mediated metabolic disorders." (PMID 38672494, 2024).
IPP also shares sentences with these, for which no sentence is quoted: cardiovascular diseases (1 paper); dyslipidemia (1); Hypercholesterolemia (1); Hyperglycemia (1); myocardial infarction (1); neuroblastoma (1); pancreatic cancer (1); renal carcinoma (1).